SP5 (Sp5 transcription factor)
Description:
Binds to GC boxes promoters elements. Probable transcriptional activator that has a role in the coordination of changes in transcription required to generate pattern in the developing embryo (By similarity).
Tractability: No criterion of Open Targets' tractability assessment is met for any kind of drug.
Gene: Protein-coding gene on chromosome 2 (170,715,337 to 170,718,078, forward strand). Ensembl gene ENSG00000204335.
Subcellular location: Nucleus
Subcellular location (Human Protein Atlas): Nucleoli; Nucleoplasm
Gene Ontology:
Molecular function: DNA-binding transcription factor activity, RNA polymerase II-specific; RNA polymerase II cis-regulatory region sequence-specific DNA binding; DNA-binding transcription repressor activity, RNA polymerase II-specific; RNA polymerase II transcription regulatory region sequence-specific DNA binding; sequence-specific DNA binding
Biological process: regulation of transcription by RNA polymerase II; negative regulation of transcription by RNA polymerase II
Cellular component: chromatin; nucleus
Genetic constraint (gnomAD): Loss-of-function variants: 12 observed, 17.44 expected, observed/expected ratio (o/e) 0.69, 90% interval 0.44 to 1.12. The synonymous counts are far from expectation, so gnomAD's model fits this gene poorly and the ratio says little. Missense variants: 644 observed, 495.27 expected, observed/expected ratio (o/e) 1.3, 90% interval 1.22 to 1.39. Synonymous variants: 321 observed, 235.92 expected, observed/expected ratio (o/e) 1.36, 90% interval 1.24 to 1.49.
Homologues: Orthologues: chimpanzee SP5 (99% identical), macaque SP5 (99% identical), dog SP5 (98% identical), mouse Sp5 (97% identical), rat Sp5 (97% identical), pig SP5 (97% identical), guinea pig SP5 (96% identical), zebrafish sp5a (63% identical), tropical clawed frog sp5 (62% identical), Caenorhabditis elegans sptf-2 (21% identical), Drosophila melanogaster luna (16% identical), Drosophila melanogaster CG3065 (14% identical). Paralogues in human: SP8 (36% identical), SP9 (34% identical), SP7 (30% identical), SP6 (29% identical), KLF11 (25% identical), KLF10 (23% identical), KLF5 (22% identical), KLF4 (20% identical), KLF1 (19% identical), KLF13 (19% identical), KLF12 (19% identical), KLF3 (19% identical), and 10 more.
Diseases named in the same sentence as SP5 in open-access papers:
SP5 is named in the same sentence as 26 diseases in open-access papers, as found by Europe PMC text mining. Sharing a sentence is not in itself a finding about the gene and the disease. The quoted sentences say what the papers report.
prostate carcinoma (4 papers, 2024 to 2025). A carcinoma that arises from epithelial cells of the prostate gland. "Notably, SP5’s association with the activation of the AKT/mTOR signal pathway in prostate cancer, hints at intriguing regulatory mechanisms governing SERPING1 transcription that warrant further investigation." (PMID 39962118, 2025). "At the molecular level, succinylation of a specific protein, for example, CPT1A, causes succinylation of SP5 at K391, which activates the master signaling pathway PDPK1-AKT/mTOR and promotes proliferation and survival of prostate cancer cells." (PMID 40865948, 2025). "Furthermore, CPT1A directly binds to SP5 and promotes its succinylation, which in turn enhances SP5's binding to the PDPK1 promoter, thereby increasing PDPK1 transcription and promoting prostate cancer progression." (PMID 40070041, 2025).
gastric cancer (3 papers, 2012 to 2024). A primary or metastatic malignant neoplasm involving the stomach. "Gene Sp5 (fold change 4.8) was reported to be overexpressed in several human tumors including hepatocellular carcinoma, gastric cancer, and colon cancer." (PMID 23148692, 2012). "Elevated expression of Sp5 was noted in several human cancers including HCC, gastric cancer, and colon cancer, and it is considered a therapeutic target for HCC." (PMID 23951254, 2013).
hepatocellular carcinoma (3 papers, 2012 to 2025). A malignant tumor that arises from hepatocytes. "Our identification of ZNF460 and SP5 as significantly enriched TF motifs, with their roles in gastric, colorectal, and hepatocellular cancers, suggests that TSp regulatory networks may be broadly dysregulated in multiple cancer types." (PMID 41279024, 2025).
liver cancer (3 papers, 2024). An epithelial or non-epithelial malignant neoplasm that arises from the liver. "By analysing ChIP-seq data for SP1, SP2, and SP5 in the liver cancer cell line HepG2 (downed from ENCODE), we found direct binding of SP1, SP2, and SP5 to the promoters of most SRTs near TSSs, which exhibited strong H3K27ac occupancy and open chromatin accessibility." (PMID 38185659, 2024). "Characterization of liver cancer pathways in tumor samples: We generated cell lines from HBL, HCC, HCN-NOS, and lung metastases patient tumors, which were resistant to cisplatin treatments and demonstrated elevated HDAC1 and Sp5 proteins." (PMID 39001363, 2024).
colorectal cancer (2 papers, 2020 to 2024). A primary or metastatic malignant neoplasm that affects the colon or rectum. "Among the identified genes, SP5, SIX4, TREX2, and SPP1 were upregulated and were adverse prognostic factors in colorectal cancer." (PMID 39309424, 2024). "In colorectal carcinoma cell lines (HCT1116), SP5 inhibits cell growth by upregulating P27, another tumor suppressor gene." (PMID 32552834, 2020).
glioblastoma (2 papers, 2020 to 2024). The most malignant astrocytic tumor (WHO grade IV). "Through the further functional enrichment analysis of dysmethylated genes, such as CXCR4, TBX18, SP5, and TMEM22, several potential pathogenic functions are found to participate in the initiation and progression of glioblastoma." (PMID 33329750, 2020).
hepatoblastoma (2 papers, 2023 to 2024). Hepatoblastoma (HB) is a malignant hepatic tumor and is the most common pediatric liver cancer. "In hepatoblastoma (HBL), HDAC1 delivered to the promoter of the p21 gene by another transcription factor, sp5, and activated p21 expression, thereby promoting the proliferation and metastasis of HBL cells." (PMID 37760477, 2023).
lung carcinoma (2 papers, 2009 to 2020). "Further, our combined prognosis showed that the combined high expression of SP5, FOXP1, ROBO1, DPP4, CDYL2, and STAMBPL1 is associated to patients’ better clinical prognosis of patients with lung cancer." (PMID 32552834, 2020). "To determine whether the lung cancer-targeting peptide SP5-2 could be used to improve the chemotherapeutic efficacy of cancer treatment, we coupled the peptide to liposomes containing anti-cancer drugs." (PMID 19137069, 2009).
migraine (2 papers, 2020 to 2022). "Several regions in the brain, such as cortex, thalamus, amygdala, hypothalamus, pons, cerebellar deep nuclei, vestibular nucleus and Sp5, are thought to be involved in migraine based on human imaging studies and known pain pathways." (PMID 33167864, 2020). "We found GPER immunoreactive fibers in the Sp5 region, which constitutes an essential part of the pain pathways activated in migraine attacks." (PMID 33167864, 2020). "Interestingly, we found AVP expression, however weaker compared to other brain areas, in Sp5 (spinal trigeminal nucleus caudalis; TNC), which constitutes an important part of the pain pathways activity in migraine attacks." (PMID 36456902, 2022).
adenoma (1 paper, 2018). A neoplasm arising from the epithelium. "Alternatively or in addition, the increase in Sp5 mRNA abundance may reflect increased numbers of adenoma cells expressing Sp5 mRNA at high levels." (PMID 30250042, 2018).
bladder cancer (1 paper, 2025). "In contrast, EV samples derived from both GCB‐sensitive and GCB‐resistant bladder cancer cell lines, including SP3 (T24 EVs), SP4 (T24GCB EVs), SP5 (5637 EVs) and SP6 (5637GCB EVs), showed no detectable GCB signal." (PMID 41159684, 2025).
brain tumor (1 paper, 2023). "To compare the data quality of RRST and standard Visium datasets obtained from the pediatric brain tumor samples, we examined the expression of WNT-signaling genes, including AXIN2, DKK4, LEF1 and CTNNB1 and two known targets of the WNT pathway SP5, GAD122,23." (PMID 36720873, 2023).
embryonic carcinoma (1 paper, 2017). "We found that induction of SP5 by WNT/β-catenin signaling was most prominent in cell types with stemness properties, including hPSCs, hPSC-derived neural progenitor cells (hNPCs), and pluripotent embryonal carcinoma cell lines (PA1 and NCCIT)." (PMID 29044119, 2017).
glioma (1 paper, 2020). A benign or malignant brain and spinal cord tumor that arises from glial cells (astrocytes, oligodendrocytes, ependymal cells). "According to recent publications, SP5 has been shown to be therapeutic target and a prognostic biomarker for multiple cancer subtypes, including glioma." (PMID 33329750, 2020).
metastasis (1 paper, 2024). The spread or migration of cancer cells from one part of the body (where they first appeared) to another. "Interestingly, an over 100-fold elevation of Sp5 was observed in the multiple recurrent lung metastasis compared to the background region." (PMID 39001363, 2024).
Townes-Brocks syndrome (1 paper, 2021). Townes-Brocks syndrome (TBS) is a rare genetic disorder characterized by the triad of imperforate anus, dysplastic ears often associated with sensorineural and/or conductive hearing impairment, and thumb malformations. "Moreover, the marker genes that we found to specifically label Duo identity include SP5 and SALL1, the latter of which has been linked to Townes-Brocks syndrome with developmental malformation of multiple organs including the limb, kidney and gastrointestinal tract." (PMID 33406262, 2021).
tumor (14 papers, 2009 to 2025). "The analysis confirmed a (moderate) increase in the expression of Ascl2 and other Wnt target genes Axin2, Lgr5, and SP5 in Apc/Msx−double-deficient tumor cells when compared to the cells with intact Msx1 gene." (PMID 30733598, 2019). "In summary, SERPING1 emerges as a novel tumor suppressor gene and SP5/SERPING1/TSC2 is a promising therapeutic target in the context of LUAD." (PMID 39962118, 2025). "Additionally, HDAC1 binding to SP5, a transcription factor, hampers the expression of the tumor suppressor protein P21, potentially promoting tumor development." (PMID 38390281, 2024). "We also found that the binding proficiency of the Sp transcription factor family (including SP1, SP2, SP4, and SP5) (Rows 17–20) could bind GC/GT-rich promoter elements by its zinc finger structure and play a critical role in tumor growth and metastasis." (PMID 37833332, 2023). "Thus, the SP5-52-VEGF ligand-receptor interaction provides a novel basis for targeted therapy of the tumor neovasculature for potentially treating solid tumors and some types of blood cancers." (PMID 32296681, 2020). "Our results indicate that the SP5-2 tumor targeting peptide may be used as imaging probes of NSCLC and targeting ligands for liposomal delivery systems to increase the efficacy of chemotherapy for NSCLC." (PMID 19137069, 2009). "SP5, a downstream target of the Wnt/β-catenin signaling pathway in colon and several other tissues, is reported to be up-regulated in CRC and to promote tumor cell growth." (PMID 30250042, 2018). "We found that some HBL and HCC tumor samples have high levels of HDAC1 and Sp5, suggesting that the HDAC inhibitor SAHA could be used to reduce the HDAC1-Sp5 pathway in HBL and HCC." (PMID 39001363, 2024). "More specifically, the SP5-52 peptide bound selectively to the vascular endothelial growth factor (VEGF) of human lung cancer surgical specimens, which resulted in tumor homing into eight different types of human tumor xenograft models." (PMID 32296681, 2020). "Interestingly, HCC lesions but not the background liver expanded as tumour organoids in vitro by forming compact structures composed of tumoural cells that filled in the lumen of the organoid and expressed high levels of WNT target genes (Axin2 and Sp5)." (PMID 35039505, 2022).
cancer (8 papers, 2009 to 2025). A tumor composed of atypical neoplastic, often pleomorphic cells that invade other tissues. "Elevated expression of SP5 has been detected in different human cancers and can downregulate many WNT target genes, resulting in a decreased transcription response." (PMID 36611892, 2022).
infection (3 papers, 2020 to 2025). The state of being infected such as from the introduction of a foreign agent such as serum, vaccine, antigenic substance or organism. "In the BS, early infection of the inferior olive (IO) and hypoglossal nucleus (12N) was noted from 4 to 24 hpi, followed by Sp5 (8–72 hpi), nucleus ambiguus (Amb; 16–24 hpi; Fig. 4III), and nucleus of the solitary tract (Sol; 16–48 hpi)." (PMID 41017005, 2025). "In one case, the SP5 pattern was mixed with another RFLP pattern (SP5 mix), probably due to laboratory contamination or mixed infection." (PMID 32578701, 2020). "In the context of AbpAB-mediated inhibition of Sp5 lysogenization, cell suicide following infection may result in a lower lysogeny rate." (PMID 37882551, 2023).
SP5 also shares sentences with these, for which no sentence is quoted: colon cancer (2 papers); colitis (1); Infertility (1); intestinal tumors (1); lung adenocarcinoma (1); male pattern baldness (1); ovarian carcinoma (1).